VIM (vimentin)
Diseases named in the same sentence as VIM in open-access papers (continued):
Sharing a sentence is not in itself a finding about the gene and the disease.
tumor (continued). "Regulation of EMT markers expression, for instance, N-cadherin, Vimentin and E-cadherin, ultimately affects tumor progression, metastasis and drug resistance." (PMID 36185284, 2022). "Our data revealed reduced expression of the epithelial markers E-cadherin and β-catenin, with a corresponding increase in the mesenchymal marker vimentin, in only leading edges of a tumor mass." (PMID 36012449, 2022). "Average tumor burden (based on positive staining for human vimentin) in the lungs of mice harboring MDA-231EV tumors were significantly higher than the average tumor burden of the lungs of mice harboring MDA-231c141 tumors." (PMID 35456497, 2022). "IHC staining of isolated tumor tissues showed that sh-circ_0000518 decreased the protein expression of Ki-67 and vimentin with elevated levels of E-cadherin." (PMID 35874898, 2022). "Vimentin was found to be overexpressed in the endothelium of a wide array of human tumor types and in syngeneic and xenograft animal tumors, by transcript and protein analysis." (PMID 35606362, 2022). "To investigate SMRwt peptide effects comparatively to Mortalin and Vimentin’s role in tumor cell progression, we transfected miRNA Mortalin and miRNA Vimentin to MDA-MB-231 and MCF-7 cells and monitored for EMT." (PMID 35915218, 2022). "The reduced expression of OXPHOS and mitochondrial translation components also correlated well with the changes in epithelial-mesenchymal transition (EMT) markers, E-cadherin (CHD1), and vimentin (VIM) in the ER/PR(+) tumor biopsies." (PMID 36119536, 2022). "This resulted in poorly differentiated, more mesenchymal tumours containing predominantly vimentin+ (Vim+) mesenchymal-like PDAC cells, less epithelial-like CK19+ glandular PDAC cells and a significantly higher number of CK19+Vim+ hybrid EMT cancer cells." (PMID 36224174, 2022). "Both tested Montanide compositions resulted in the induction of anti-vimentin antibodies and significant tumor growth reduction in the murine B16F10 melanoma model, as compared to mice that received a control vaccine." (PMID 35681575, 2022). "Regarding immunohistochemistry, the tumor tended to be positive for vimentin (100%; n = 35/35), CD34 (63.4%; n = 26/41), ER (50%; n = 16/32), and PR (53.3%; n = 16/30), while S-100 showed 91% negativity (n = 41/45)." (PMID 35860056, 2022). "With the exception of a report from our lab, wherein we showed that vimentin expression at the invasive front of OSCC tumor sections significantly correlated with local recurrence, vimentin has not been directly linked to untreatable, recurrent OSCC." (PMID 35207438, 2022). "We then evaluated vimentin, the major cytoskeletal component of motile mesenchymal cells including metastatic tumor cells of epithelial origin." (PMID 35887021, 2022). "The pro-tumorigenic effects of vimentin have been attributed to intracellular functions in tumour cells so far." (PMID 35606362, 2022). "An immunohistochemical (IHC) panel inclusive of p63, SOX-10, S-100, calponin, vimentin, and Ki-67 was done to evaluate the tumour and grade PAC." (PMID 35505695, 2022). "Reduced E-cadherin and its cytoplasmic expression associated with histologic differentiation and the advancing edge of the tumor are inversely correlated with vimentin reactivity which is increased with tumor differentiation and invasive fronts." (PMID 36321045, 2022). "Staining for vimentin and cyclin D1 was seen within tumor cells at the front of invasion in 100 and 84.4% of the tumors, respectively." (PMID 34495397, 2022). "The IHC studies showed that the tumor cells were mostly positive for vimentin, desmin, estrogen receptors (ER) and progesterone receptors (PR), while weak expression of SMA was also noticed." (PMID 36262943, 2022). "It is a human IgG1 kappa antibody that binds to tumor cell ectodomain vimentin antigen for its anti-cancer effects." (PMID 35573702, 2022).
tumor (continued). "More importantly, the EMT program was indeed found in the surviving tumor cells, reflected by enhanced expression of Vimentin and reduced expression of E-Cad in tumors treated with BVD." (PMID 36276640, 2022). "AKT1 kinase binds to and phosphorylates vimentin, preventing vimentin from caspase-induced proteolysis and ultimately leading to an increase in motility and invasiveness, as well as enhanced tumour growth and metastasis." (PMID 35932303, 2022). "qPCR indicated that tumor markers N-cadherin, Vimentin, HER-2, CEA, CA15-3 and SF were higher in dogs with malignant tumors than healthy dogs, with a low level of E-cadherin in malignant tumors." (PMID 36359174, 2022). "In CRC, the mesenchymal markers, N-cadherin and vimentin, have been shown to drive malignant progression of tumor cells and to correlate with metastasis development and a worse OS in patients." (PMID 36555840, 2022). "In order to confirm these observations, CXCR4 and human vimentin co-immunofluorescent staining was performed on the tumor samples." (PMID 35456719, 2022). "Quantification of these results showed a high level of correlation between the NK cells in tumor and vimentin in cancer cells." (PMID 36032170, 2022). "In G2, CD56, CgA, NSE, vimentin and Ki-67 were higher in tumour tissue compared to those in non-tumour, and levels of CD44, CD45, CK7, DAXX, synaptophysin and PDX1 were lower in tumour tissue relative to those in non-tumour tissue." (PMID 36362433, 2022). "Anti-human CXCR4 or anti-human vimentin antibodies were shown to be specific and highly sensitive markers in tumor cells in our CXCR4+ model." (PMID 35884987, 2022). "Although vimentin overexpression has been correlated with augmented tumor growth, invasion, and unfavorable prognosis, the overall relevance of this molecule is not yet clear." (PMID 35804883, 2022). "E-cadherin, a key biomarker of EMT plays a role as a tumor suppressor, while N-cadherin and Vimentin act as tumor promotors." (PMID 35418191, 2022). "Α-SMA and Vimentin were expressed in the tissue surrounding the tumor, and their colocalization suggests the presence of human CAFs." (PMID 36443822, 2022). "We conducted immunohistochemical analysis to detect the expression of E-cadherin, vimentin, β-catenin, and Ki67, and found that CxSCC tumor buds displayed decreased levels of E-cadherin, Ki67, and membranous β-catenin, and increased levels of vimentin." (PMID 35860042, 2022). "Following the pattern observed in heparanase and MMP9 levels, vimentin showed a tendency to decrease in stage III when compared to stage II in tumor tissue." (PMID 36139645, 2022). "Recent studies have revealed that vimentin can be translocated to the surface of very aggressive tumor cells, such as metastatic cells." (PMID 35320951, 2022). "Meanwhile, Vimentin is an intermediate fibrous-type protein that increases the motility of the tumor cells and is highly expressed when the EMT process occurs." (PMID 35889427, 2022). "Four days of co-culturing with tumor cells induced an increase in the expression of both vimentin and αSMA in HUVECs." (PMID 36077778, 2022). "Real-time PCR analysis showed that after lncRNA KCNQ1OT1 was knocked out, the expression of E-cadherin in nude mouse tumor tissues was significantly increased, whereas the expression of Vimentin in nude mouse tumor tissues was significantly decreased." (PMID 35432529, 2022). "Further immunohistochemistry assays showed that FTO knockdown inhibited the expression of Vimentin and E-cadherin, indicating an inhibiting effect of tumor metastasis, whereas ERBB2 has a reverse effect." (PMID 35524932, 2022). "Vimentin plays an important role in tumor invasion and metastasis, and its counter-regulation is a further evidence of the role that LIF/LIFR signaling plays in the modulation of EMT process." (PMID 35847866, 2022).
tumor (continued). "To further verify the effect of RT on B16F10 metastasis, we detected the expression of tumor metastasis-related genes twist, snail, vimentin, and N-cadherin by qPCR." (PMID 36014573, 2022). "GSCs isolated from human LN18 cells with cell surface vimentin overexpression have been found to present 95% CD133 expression and 98% CD44 expression, suggesting that GSCs that express surface vimentin possess tumor-initiating properties." (PMID 36362359, 2022). "In many cancers, tumour development and metastasis are connected with increased Vimentin expression and reduced E‐cadherin expression." (PMID 36420658, 2022). "Another set of tri-marker (CD133/CD31/Vimentin)-iFISH which focused on the progenitor feature of the tumor demonstrated that cancer stem-like cells displayed a CD45-/CD31-/CD133+/Vimentin- phenotype." (PMID 35311070, 2022). "Vimentin and αSMA in tumor tissues can be expressed by cancer cells, presumably through EMT, or by resident stromal cells such as fibroblasts." (PMID 35628489, 2022). "The ERK pathway promotes tumor cell proliferation and metastasis by stimulating the expression of matrix metalloproteinases and vimentin." (PMID 35563845, 2022). "To further analyze EMT by studying the localization of KRT and vimentin expression in more detail, we subjected EcPV2-positive and EcPV2-negative tumor sections to double IF staining for these molecules." (PMID 35215208, 2022). "TGF-β signaling and Wnt/β-catenin signaling can promote the EMT process by increasing the expression of N-cadherin and Vimentin or decreasing the expression of E-cadherin, thereby promoting tumor invasion and metastasis." (PMID 35280775, 2022). "Hypoxia-induced activation of the SMAD3 pathway through increased SMAD3 bioavailability and recruitment to the adapter protein SARA induced tumor progression and cancer cell invasion, events associated with the expression of SMAD3 gene targets ITGB2 and VIM." (PMID 35681731, 2022). "Specifically, tumor cells were positive for CK 18/19 as well as vimentin, supporting the EMT-mediated mesenchymal state." (PMID 35163206, 2022). "The anti-vimentin approach overcomes tumor immune suppression by enhancing infiltration, and altering the composition, of immune cells in the tumor area." (PMID 35606362, 2022). "CD10 and vimentin were positively stained in ccRCC‐1, ccRCC‐6 and pRCC‐1 tumour–organoid pairs, in agreement with their proximal tubule origin." (PMID 35802820, 2022). "Results of E-cadherin expression detection showed that, after LIMK1 silencing, the expression of E-cadherin in tumor tissues increased, while that of Vimentin decreased." (PMID 35265128, 2022). "This protocol was originally developed to capture cell-surface vimentin (CSV)-positive circulating tumor cells (CTCs) using conventional antibody-antigen interaction mechanics." (PMID 36201506, 2022). "In a study of patients with Grade 1 and 2 NENs, approximately 25% tumour tissues expressed vimentin." (PMID 36362433, 2022). "(A) and (B) Representative images of human vimentin-stained xenograft tumours with overlayed image analysis." (PMID 36412091, 2022). "Stromal cell infiltration was confirmed with vimentin staining which indeed showed high positivity in both s.c. tumor types." (PMID 36355420, 2022). "They reported all tumours as having diffuse expression of vimentin, whilst 25 (96.2%) expressed neuron-specific enolase (NSE), 24 (92.3%) expressed laminin and 25 (96.2%) expressed GFAP." (PMID 36290122, 2022). "ZEB2 and Vimentin staining in L6 were clearly located in tumor pseudocrypts, further supporting a more pronounced EMT state of tumor cells." (PMID 35837106, 2022). "Together, these data indicate that vimentin is a negative regulator for both tumor initiation and tumor growth in CAC." (PMID 35399505, 2022).
tumor (continued). "Among the vimentin positive tumors, 48.3% (43/89) had a tumor size > 2 cm compared to 25.9% (15/58) of vimentin positive immune-expression in tumors of size less than 2 cm which was (p = 0.009; χ2 = 9.394)." (PMID 35498535, 2022). "Of note, we also found a high residual effect for GSTM1 and VIM, two genes known to support tumor progression and metastasis." (PMID 35565214, 2022). "Almost all (9/10) cases showed strong reactivity of the tumor cells with vimentin stain (one case had moderate staining)." (PMID 35778593, 2022). "Human vimentingIHC staining revealed that nanotoxin repeated administration clearly diminished the number of cancer cells (vimentin+) in the tumor invasive front." (PMID 35456719, 2022). "This lower expression of epithelial markers in the ITF and the presence of a few N-cadherin and vimentin immunolabelled cells was indicative of an EMT process in the tumor cells, predicting the biological behavior of canine SCCs." (PMID 36669020, 2022). "In conclusion, extracellular vimentin secreted by tumor ECs is a crucial player in tumor angiogenesis, immune infiltration, and immune suppression." (PMID 35606362, 2022). "Our study showed a slight increase of GSK3β phosphorylation, which inhibits GSK3β activity as a kinase and decreased the phosphorylation of its targeted protein, β-catenin, in the tumor of vimentin null mice." (PMID 35399505, 2022). "All tumours demonstrated positive staining for vimentin, 20 were positive staining for S100, and four for desmin." (PMID 36290122, 2022). "Expression of β-catenin and vimentin was found to be higher in the tumor regions of mice with high CTSK expression while the expression of E-cadherin was low." (PMID 36138018, 2022). "By western blotting analysis, we found that quercetin reduced the expression of N-cadherin and vimentin expression, while induced the expression of E-cadherin in subcutaneous tumor tissues." (PMID 36386155, 2022). "Further, in areas of tumor budding, significant deregulation of E-cadherin and vimentin expressions was also noted." (PMID 36321045, 2022). "Overexpression of vimentin correlates with accelerated tumor growth, invasion, and a poor prognosis in some cancers." (PMID 35800070, 2022). "Tumor grade progression was closely correlated with LVI (R = 0.2113, p = 0.0338), expression of vimentin (R = 0.5344, p = 0.000), tumor budding (r = 0.4867, p = 0.000), Β-catenin (R = 0.410, p = 0.044), and lack of E-cadherin (R = 0.2950, p = 0.0028)." (PMID 36143062, 2022). "The remainder of the G2 cohort tumours were metastatic and had lower levels of differentiation markers and higher vimentin expression." (PMID 36362433, 2022). "The results showed that the expressions of N-cadherin and Vimentin were up-regulated in tumor cells stimulated by higher hardness, while the expression of E-cadherin showed the contrary." (PMID 36355508, 2022). "Citrullinated vimentin peptide vaccines delayed tumor growth and increased survival rates of HLA-DR4 transgenic mice implanted with B16F1 tumors expressing HLA-DR4." (PMID 36077528, 2022). "To further characterize EcPV2-positive and –negative HNSCCs with respect to the localization of KRT and vimentin expression, we analyzed tumor sections by IF KRT/vimentin double-staining and generated high-resolution images." (PMID 35215208, 2022). "The immunohistochemical results showed that GWH extracted increased E-cadherin expression in SCG7901 cells and inhibited tumor growth factor Ki67and Vimentin." (PMID 35281866, 2022). "Vaccination with a conjugate vaccine targeting extracellular vimentin was previously shown to induce a potent humoral immune response and tumor growth inhibition in mice." (PMID 35681575, 2022). "We also validated these results at the protein level using multitarget immunofluorescence staining to label E-cadherin and vimentin in the patient tumor tissues and the paired para-carcinomous tissues with fluorescently labeled antibodies." (PMID 35463314, 2022).
tumor (continued). "LPA activates LPAR1, which activates 74 different genes that are important in tumor progression, invasion, and metastasis, for example, vimentin (VIM)." (PMID 35814375, 2022). "Overexpression of TGF-β that secreted by TAMs interacted with different transcription factors such as Snail and Slug to induce EMT in tumor cells through down-regulation of E-cadherin expression, and up-regulation of vimentin expression." (PMID 36374927, 2022). "EMT is manifested by the loss of E-cadherin and increased expression of Vimentin and SOX9, thus promoting tumor invasion." (PMID 35688943, 2022). "The expression of TROY, E-cadherin, and vimentin in tumor samples obtained from nine NSCLC patients who were resistant to the first-generation EGFR-TKI and without T790M mutation were determined by immunohistochemistry staining." (PMID 35646083, 2022). "Epithelial-mesenchymal transition (EMT) is key step of tumor metastasis characterized by the expression level of epithelial marker E-cadherin and mesenchymal marker Vimentin." (PMID 35013118, 2022). "In xenografted mice, silencing RPN2 expression reduced tumor growth, ROS production, and levels of Ki-67, Vimentin, LDHA, and p-Akt/Akt, but enhanced E-cadherin expression." (PMID 35156537, 2022). "We recently showed that vimentin is specifically excreted by angiogenic tumor endothelial cells and plays a stimulatory role in the process of tumor angiogenesis, making it a promising candidate for anti-cancer vaccination." (PMID 35681575, 2022). "The similar observation was revealed when PDAC organoids were co-cultured with tumor fibroblast and after co-staining presence of vimentin in CAF (red stain) and αSMA was identified in cancer associated fibroblasts." (PMID 36713532, 2022). "Extracellular vimentin was previously shown to be a specific and promising target of the tumor vasculature." (PMID 35681575, 2022). "We have recently shown that extracellular vimentin is overexpressed and secreted by tumor endothelial cells and that anti-vimentin antibodies are capable to inhibit tumor growth in several in vivo murine tumor models." (PMID 35681575, 2022). "During EMT, tumor cells lose the epithelial marker E-cadherin and gain mesenchymal markers, such as Snail1 and vimentin, and these effects are abolished by the overexpression of Sema3A." (PMID 35775491, 2022). "Taken together, these antibody-based studies show the potential of inhibiting tumor angiogenesis and tumor growth by targeting extracellular vimentin secreted by the tumor endothelium, which we approach by vaccination as presented below." (PMID 35606362, 2022). "Vimentin has been shown as a predictive biomarker for tumor growth and metastasis, although its understanding is limited in OTSCC prognosis." (PMID 35498535, 2022). "High expression of SNORA71A significantly suppressed the E‐cadherin and increased Vimentin in the tumor tissues of mice." (PMID 35100495, 2022). "Our lab has shown the role of aberrant vimentin expression in tumor cut margins to be significantly correlated to lymph node metastasis in OSCC." (PMID 35207438, 2022). "In the LuCaP35 PDX model, castration led to EMT in the tumours, a change in phenotype that was characterised by a decrease in E-cadherin coupled with an increase in N-cadherin and vimentin protein levels." (PMID 35493092, 2022). "Our results demonstrated that 6-gingerol treatment inhibited HIF-1α target genes, including MMP-9, vimentin and snail, which are correlated with tumor metastasis." (PMID 35408505, 2022). "For further experiments, morphology, and expression of CK8 and vimentin changed according to the original tumour grade." (PMID 35102500, 2022). "Immunostaining of vimentin, a representative marker of cell mesenchymal phenotype, was weakened in tumor tissues from sh-SKA1-infected 786-O cells, which is consistent with in vitro results." (PMID 36462498, 2022).